CD1D (CD1d molecule)
Diseases named in the same sentence as CD1D in open-access papers (continued):
Sharing a sentence is not in itself a finding about the gene and the disease.
steatosis (3 papers, 2011 to 2022). Increased lipid within the cytoplasm of cells. "CD1d deficiency led to a mild exacerbation of steatosis during high fat or choline-deficient feeding, accompanied by impaired hepatic glucose tolerance." (PMID 21980475, 2011). "CD1d−/− mice were relatively resistant to steroid-induced steatosis, suggesting that NKT cells play a role in fat accumulation." (PMID 35392825, 2022). "Steroid-mediated steatosis was CD1d-dependent, while steroidinducedliver necrosis, inflammation, and metabolic changes were CD1d-independent." (PMID 35392825, 2022). "However, while CD1d−/− mice showed less steroid-mediated steatosis, GC treatment exerted a more profound effect on reducing steatosis in these mice compared with WT mice." (PMID 35392825, 2022). "The beneficial effect of GC to alleviate the steroid induced-metabolic changes and liver damage were independent of CD1d, while CD1d prevented the ability of GC to reduce steroid-mediated steatosis." (PMID 35392825, 2022). "The present study supports a role for CD1d in the development of steatosis per se while not preventing steroid-mediated hepatocyte damage or metabolic derangements." (PMID 35392825, 2022). "However, CD1d−/− mice did not manifest marked steroid-induced steatosis." (PMID 35392825, 2022).
T cell lymphoma (3 papers, 2012 to 2021). "Our previous studies have shown enhanced survival in CD1d-deficient mice when they were inoculated with RMA/S T-cell lymphoma cells." (PMID 29354122, 2017). "EL-4 cells are mouse T cell lymphoma-derived cells which express CD1d and when injected into mice are directly killed by a mechanism requiring NKT cells." (PMID 34799646, 2021).
anaplastic thyroid carcinomas (2 papers, 2019 to 2021). "Most astonishingly, CD1d expression disappeared from the cellular surface and was detected rather in the cytoplasm of anaplastic thyroid carcinoma cells." (PMID 31560833, 2019). "Anaplastic thyroid carcinomas show significantly higher expression of CD1d, a receptor for NKT cells, which are subject of several anticancer therapy studies." (PMID 31560833, 2019). "Moreover, a recent study examined CD1d levels in anaplastic thyroid carcinomas and observed significantly higher levels of CD1d, compared to normal thyroid tissue, implicating a potential role for NKT cell-based therapy in this disease as well." (PMID 34072042, 2021).
breast tumor (2 papers, 2011 to 2024). "Thus, unlike other CD1d-deficient tumors, treatment of CD1d-expressing breast tumors with an anti-CD1d blocking antibody significantly increases spontaneous tumor metastasis in vivo, demonstrating the importance of CD1d expression for iNKT-mediated antitumor immunity." (PMID 21695190, 2011). "The ability of CD1d-restricted NKT cells to regulate tumor growth and metastasis of CD1d-expressing breast tumors has yet to be explored." (PMID 21695190, 2011). "CD1d-expressing cancer cells in the primary breast tumor may provoke similar defects in iNKT function." (PMID 21695190, 2011). "As demonstrated in our study, treatment of mice bearing CD1d-expressing breast tumors in vivo with an anti-CD1d blocking antibody did not inhibit tumor progression, but instead significantly increased spontaneous lung metastasis." (PMID 21695190, 2011). "However, the efficacy of this treatment strategy for CD1d-expressing breast tumors has not been verified." (PMID 21695190, 2011).
cardiac hypertrophy (2 papers, 2012 to 2021). "Use of CD1d-deficient mice indirectly proved a role for iNKT cell in cardiac hypertrophy." (PMID 34368120, 2021). "In Ang-II infusion-induced cardiac hypertrophy, administration of recombinant IL10 to CD1d-deficient mice fully reversed the adverse phenotypes of these recipient mice." (PMID 34368120, 2021).
chlamydial infection (2 papers, 2015 to 2025). "On the other hand, the detrimental role of NKT cells in chlamydial infection has been mostly reported in the studies using CD1d-KO mice that are in BALB/c background and have deficiency in both iNKT and type II NKT cells." (PMID 26029217, 2015). "NKT cells are activated during chlamydial infection when APCs present lipid antigens on CD1d." (PMID 41305402, 2025). "Notably, the protective and detrimental role of NKT cells in chlamydial infection was mostly shown in Jα18-KO and CD1d-KO mice, respectively." (PMID 26029217, 2015).
dengue (2 papers, 2014 to 2024). "Given the differential protective responses during homologous and heterologous secondary infections with dengue, we tested the influence of antibodies produced in WT or CD1d-KO mice with both types of challenge." (PMID 39088280, 2024). "Next, we questioned whether the ADE observed with IgG from CD1d-KO mice could worsen dengue disease." (PMID 39088280, 2024). "Furthermore, when comparing between patients with different dengue disease severity, the level of monocyte CD1d expression at day -1 was higher in DHF than in healthy control (10504; 9704–13541) (p = 0.01), but not significantly higher than that of DF (p = 0.27)." (PMID 24945350, 2014).
food allergies (2 papers, 2018 to 2022). "With food allergies, lipids associated with aeroallergens have also been shown to influence allergic sensitization via CD1d-restricted iNKT cell activation." (PMID 35495627, 2022). "Four of the 10 food allergy studies report lipid presentation by CD1d molecules, with three of these also reporting the activation of iNKT cells." (PMID 35495627, 2022).
gastric cancer (2 papers, 2015 to 2021). A primary or metastatic malignant neoplasm involving the stomach. "PBMCs from gastric cancer patients were stained with various combinations of monoclonal antibodies to proteins which have been suggested for use in identifying Bregs, including: CD5, CD1d, CD38, CD24, IgM, CD25, CD10, and CD21." (PMID 26378021, 2015).
Hypertension (2 papers, 2021 to 2025). The presence of chronic increased pressure in the systemic arterial system. "CD1d-dependent NKT cells showed protective effects in hypertension and cardiac remodeling, suggesting that different types of NK cells may play different roles in hypertension." (PMID 40134277, 2025). "DCs lacking CD1d reduce IL-10 production by NKT cells, and the administration of IL-10 to CD1d-KO mice may significantly reverse Ang II-induced hypertension and cardiac remodeling by activating STAT3 and inhibiting the TGF-β1 and NF-kB signaling pathways." (PMID 33612829, 2021).
hypertriglyceridemia (2 papers, 2018 to 2022). A laboratory test result indicating elevated triglyceride concentration in the blood. "Steroid administration to CD1d−/− mice was associated with hyperglycemia and hypertriglyceridemia." (PMID 35392825, 2022). "The steroid-associated hyperglycemia and hypertriglyceridemia were independent of CD1d." (PMID 35392825, 2022).
intestinal inflammation (2 papers, 2012 to 2022). "B cells expressing high levels of CD1d and CD5 have been linked to the regulation of chronic intestinal inflammation, experimental arthritis, and T cell-mediated inflammation through IL-10 secretion." (PMID 23071588, 2012).
lysosomal storage disease (2 papers, 2017 to 2019). A metabolic disorder caused by mutations in proteins critical for lysosomal function, including lysosomal enzymes, lysosomal integral membrane proteins, and proteins involved in the post-translational modification and trafficking of lysosomal proteins. "For example, the increased levels of C16-SLs in CerS2 null thymocytes might affect lysosomal loading of other self-antigens onto CD1d, as occurs in some mouse models of lysosomal storage diseases, where massive accumulation of SLs and GSLs occurs." (PMID 29163475, 2017). "Several other mouse models of the lysosomal storage disease (Tay-Sachs, GM1 gangliosidosis, Fabry, NCP1) also show a reduced number of type I NKT cells, not due to defective CD1d presentation or lack of APCs, but due to impaired loading of lipid antigen on to the CD1d molecule." (PMID 31620124, 2019).
malignant glioma (2 papers, 2011 to 2019). A grade III or grade IV glioma arising from the central nervous system. "Although direct anti-tumor lysis mediated by NK cells has been reported to be restricted to tumor cells that display CD1d protein on their surface, malignant gliomas have been shown to express CD1d." (PMID 30991681, 2019).
Neonatal sepsis (2 papers, 2018). Systemic inflammatory response to infection in newborn babies. "We then used CD1d knockout neonatal mice to demonstrate that KRN acts through the major histocompatibility complex-like molecule CD1d to improve outcomes in neonatal sepsis." (PMID 29720984, 2018).
osteosarcoma (2 papers, 2017 to 2022). A usually aggressive malignant bone-forming mesenchymal neoplasm, predominantly affecting adolescents and young adults. "In addition, in naturally expressing CD1d+ human osteosarcoma cell lines, iNKT cells selectively killed the tumor cells through Fas-FasL interaction, while leaving cocultured CD1d− osteoclasts and CD1d+ mesenchymal stem cells unaffected." (PMID 29326711, 2017). "Furthermore, human iNKT cells have been reported to kill CD1d+ osteosarcoma cells, but not CD1d− osteoblasts, confirming the CD1d restriction of iNKT cell–dependent cytotoxicity." (PMID 35757002, 2022).
periodontitis (2 papers, 2014 to 2021). An acute or chronic inflammatory process that affects the tissues that surround and support the teeth. "Thus, the pathogenic role of NKT cells during periodontitis could be tightly linked to the activity of B lymphocytes, both in their role as CD1d-restricted APCs and as antibody-producing effector cells." (PMID 34594157, 2021). "Interestingly, when periodontitis was induced in CD1d−/− mice, oral inoculation of P. gingivalis triggered lesser alveolar bone resorption as compared with periodontitis induced in wild-type mice." (PMID 34594157, 2021). "This indicates that other APCs that share the CD1d molecule could be involved in the antigenic presentation and activation of NKT cells during periodontitis." (PMID 34594157, 2021). "However downregulation of CD1d in murine T cells by P.g has been demonstrated implying that even though there may be higher numbers of natural killer T cells in periodontitis, they may not be functional." (PMID 24963400, 2014).
polyp (2 papers, 2017 to 2019). A usually exophytic mass attached to the underlying tissue by a broad base or a thin stalk. "We investigated gene expression levels of CD1D in a set of 184 paired normal and carcinoma samples and 34 polyp samples of which cDNA from fresh-frozen tissue was available." (PMID 28931069, 2017). "Also the polyp samples showed transcriptional downregulation of CD1D, albeit less than the carcinoma samples (student’s T-test, P = 1.2×10−3), indicating that CD1D downregulation occurs early during tumorigenesis." (PMID 28931069, 2017).
renal carcinoma (2 papers, 2021 to 2025). A carcinoma arising from the epithelium of the renal parenchyma or the renal pelvis. "Another study in which renal carcinoma cells (RCC) were evaluated for their expression of CD1d showed that CD1d was highly expressed in RCCs." (PMID 34072042, 2021).
sarcoidosis (2 papers, 2014 to 2022). Sarcoidosis is a multisystemic disorder of unknown cause characterized by the formation of immune granulomas in involved organs. "Defective IL‐10 production and T‐cell suppression by sarcoidosis monocytes could be restored following their coculture with iNKT cells, in a CD1d‐ and cell contact‐dependent process." (PMID 24723379, 2014).
thymoma (2 papers, 2017 to 2019). A neoplasm arising from the epithelial cells of the thymus. "To this end, we introduced human CD1d and CD80 into the murine thymoma cell line BW5147 (BW)." (PMID 31092850, 2019).
thyroid cancer (2 papers, 2019 to 2025). "In this study, the expression of CD1d and lymphocyte infiltration in healthy thyroid tissue as well as in several thyroid carcinomas was analyzed in order to find new targets for an immunotherapy approach." (PMID 31560833, 2019). "Additionally, different thyroid carcinomas were stained for CD1d expression." (PMID 31560833, 2019).
tularemia (2 papers, 2015 to 2018). Tularemia is an infection caused by the bacterium Francisella tularensis. "The resistance of Cd1d−/− mice to tularemia is mainly associated with enhanced formation of tertiary lymphoid structures in lungs of infected mice associated with mitigated inflammation including reduced pro-inflammatory cytokines and inflammatory cell recruitment." (PMID 30116242, 2018). "Thus, decreased neutrophilia incited by LVS infection in CD1d-/- mice could be one cause for their increased resistance to tularemia." (PMID 26068662, 2015). "Taken together, these data strongly support a detrimental function of NKT cells in pneumonic tularemia and show that CD1d-/- mice are better model than Jα18-/- mice to study the role of NKT cells in disease." (PMID 26068662, 2015).
ulcerative colitis (2 papers, 2013 to 2023). An inflammatory bowel disease involving the mucosal surface of the large intestine and rectum. "In ulcerative colitis the high levels of IL-13 are shown to be derived from variant CD1d-restricted NKT cells and IL-13 has been shown to have a toxic effect on colonic epithelial cells." (PMID 23690672, 2013).
abscesses (1 paper, 2009). "Here we show that the specific activation of iNKT cells using α-galactosylceramide (α-GalCer) induces a significant reduction in the sizes of ALA lesions, whereas CD1d−/− mice develop more severe abscesses." (PMID 19436711, 2009).
acute leukemia (1 paper, 2014). A clonal (malignant) hematopoietic disorder with an acute onset, affecting the bone marrow and the peripheral blood. "Therefore, the present study questioned whether APCs may be abnormal in the peripheral blood (PB) of acute leukemia (AL) patients, particularly the levels of CD1d." (PMID 25009659, 2014).
allergic asthma (1 paper, 2024). A asthma with a basis in a pathological type I hypersensitivity reaction. "(2003) used Cd1d−/− and Ja281−/− mice (both strains lacking iNKT cells) to establish an allergic asthma model, observing a reduced airway eosinophilia and diminished OVA-specific IgE production, without development of AHR." (PMID 38629075, 2024).
Alzheimer disease (1 paper, 2024). A progressive, neurodegenerative disease characterized by loss of function and death of nerve cells in several areas of the brain leading to loss of cognitive function such as memory and language. "In Alzheimer's disease, there have been no studies focused on changes in CD1d expression in the brains of patients or how their levels may compare to healthy controls." (PMID 39720231, 2024).
aneurysm (1 paper, 2018). Bulging or ballooning in an area of an artery secondary to arterial wall weakening. "In this study we show for the first time that a deficiency in CD1d-dependent NKT cells, a distinct subset of lipid sensing T cells, leads to a substantial reduction in the incidence and severity of aneurysms in the Ang II infusion model for AAA in mice." (PMID 29346401, 2018). "Altogether, these data prove that CD1d-dependent NKT cells contribute to AAA development in the Ang II-mediated aneurysm model by enhancing aortic degradation, establishing that therapeutic applications which target NKT cells can be a successful way to prevent AAA development." (PMID 29346401, 2018).
anti-phospholipid syndrome (1 paper, 2013). "There is a need for caution, however, as some CD1d-restricted T-cells might activate anti-phospholipid B cells and might induce or worsen anti-phospholipid syndrome, which manifests with vascular thrombosis and loss of pregnancy." (PMID 23531237, 2013).
antibody deficiency (1 paper, 2024). "Additionally, and in contrast to patterns of MHCII expression on IECs, results from our experiments indicate that antibody deficiency is associated with reduced CD1d expression in FC ISCs." (PMID 38803492, 2024).
aortic atherosclerosis (1 paper, 2018). A atherosclerosis that involves the aorta.
blepharitis (1 paper, 2025). Inflammation of the eyelids near the eyelashes. "Importantly, in CD1d−/− mice, which lack all NKT cells, UL56-deficient HSV-1 infection did cause clear inflammation and mild blepharitis (right channel), suggesting that the NKT cells in hCD1d-KI mice efficiently suppressed the replication and pathogenesis of UL56-deficient virus." (PMID 40047437, 2025).
brain tumors (1 paper, 2023). "Specifically, in pediatric brain tumors, the downregulation of MHC-I and CD1d has been documented." (PMID 37509316, 2023).
Chagas cardiomyopathy (1 paper, 2024). A disease of the cardiac muscle developed subsequent to the initial protozoan infection by trypanosoma cruzi. "CD1d+ monocytes from CARD are inflammatory and associated with DNT-cell activation, confirming that CD1d is a target for modulatinginflammation in Chagas cardiomyopathy." (PMID 39570155, 2024). "The expression of PD-1 and Fas-L by CD1d+ monocytes may contributeto the control of long-lasting Chagas cardiomyopathy." (PMID 39570155, 2024).
cholangiocarcinoma (1 paper, 2025). A carcinoma that arises from the intrahepatic biliary tree (intrahepatic cholangiocarcinoma) or from the junction, or adjacent to the junction, of the right and left hepatic ducts (hilar cholangiocarcinoma). "Recent work in aggressive cholangiocarcinoma further revealed that Vorinostat (histone deacetylase inhibitor) restores iNKT function by reversing epigenetic silencing of CD1d and upregulating its expression." (PMID 40698085, 2025).
cholangitis (1 paper, 2023). An acute or chronic inflammatory process affecting the biliary tract. "CD1d−/−dnTβRII mice, which lack CD1d-restricted NKT cells, exhibit significantly decreased hepatic lymphoid cell infiltrates and milder cholangitis compared with CD1d+/−dnTβRII mice." (PMID 36750317, 2023).
Chronic colitis (1 paper, 2013). A chronic inflammatory disease of the large intestine (colon, cecum and rectum). "The Breg subset characterized by increased CD1d expression was first identified in a mice model of chronic colitis in which CD1dhi B cells produced IL-10 and suppressed the progression of intestinal inflammation through the repression of IL-1 and STAT3 activation in a CD1d-dependent manner." (PMID 24019869, 2013).
chronic obstructive pulmonary disease (1 paper, 2023). A chronic and progressive lung disorder characterized by the loss of elasticity of the bronchial tree and the air sacs, destruction of the air sacs wall, thickening of the bronchial wall, and mucous accumulation in the bronchial tree. "In chronic inflammatory lung disease, pathogenic IL-13 producing macrophages are stimulated by a CD1d-dependent iNKT cell interaction both in experimental models as well as in chronic obstructive pulmonary disease (COPD) patients." (PMID 37818376, 2023).
chronic pancreatitis (1 paper, 2022). A chronic inflammatory process causing damage and fibrosis of the pancreatic parenchyma. "Compared with healthy people and chronic pancreatitis patients, the AUC value of CD1D methylation in the pancreatic juice of PC patients was 0.92, with a sensitivity of 75% and a specificity of 95%." (PMID 35761336, 2022). "Furthermore, a case–control study on CD1D DNA methylation was performed in 61 PC patients (stage I, II), 22 patients with chronic pancreatitis, and 19 healthy people with pancreatic juice specimens." (PMID 35761336, 2022).